HLA-DQA1 (major histocompatibility complex, class II, DQ alpha 1)
Diseases named in the same sentence as HLA-DQA1 in open-access papers (continued):
Sharing a sentence is not in itself a finding about the gene and the disease.
metabolism (1 paper, 2025). "Conversely, HLA-DQA1 was associated with increased risk for five diseases, most prominently Iron metabolism disorders (P = 1.50 × 10-8, OR = 1.60) and Disorders of mineral metabolism (P = 2.76 × 10-3, OR = 1.21)." (PMID 41202080, 2025).
microscopic polyangiitis (1 paper, 2023). Microscopic polyangiitis (MPA) is an inflammatory, necrotizing, systemic vasculitis that affects predominantly small vessels (i.e. small arteries, arterioles, capillaries, venules) in multiple organs. "First, the association of HLA-DQA1*03:02 with susceptibility to MPO-AAV and microscopic polyangiitis (MPA) and its relationship with previously reported DRB1*09:01 and DQB1*03:03 were examined in 440 Japanese patients and 779 healthy controls." (PMID 36969218, 2023).
Miscarriage (1 paper, 2023). A pregnancy that ends at a stage in which the fetus is incapable of surviving on its own, defined as the spontaneous loss of a fetus before the 22th week of pregnancy. "The prevalence of HLA-DQA1*5 allele carriage was elevated in women with miscarriages as well as those with IVF-ET failures (52.6% and 61.8%, respectively; p=0.206)." (PMID 36968684, 2023). "In our study, the presence of the HLA-DQA1*5 allele in both spouses increased the probability of high (>50%) overall HLA-DQA1 couple compatibility by a factor of 24.3 in the miscarriage group, whereas the corresponding odds were 10.5-fold higher for the IVF-ET failure group." (PMID 36968684, 2023). "Trophoblast antigenic composition is mainly represented by antigens histocompatibility in the II class, including HLA-DQA1 genes, allowing them to be used as immunological markers of recurrent miscarriage incidence." (PMID 36968684, 2023). "In our sample, the CD4/CD8 ratio was statistically significantly positively correlated with the (%) NK cell proportion in the total population and among women with IVF-ET failures and with the (%) HLA-DQA1 sharing in the group with miscarriages." (PMID 36968684, 2023). "The CD4/CD8 ratio showed positive correlations with the (%) NK cell proportion among women with IVF-ET failures and with the (%) HLA-DQA1 sharing in the group with miscarriages, which translates into a trend of co-existence of immunological risk factors in this population." (PMID 36968684, 2023).
neonatal lupus erythematosus (1 paper, 2022). A self-limited skin rash that appears in the neonatal period and usually resolves in four to six months after birth. "The HLA-DQA1 alleles have also been studied in neonatal lupus erythematosus (NLE), with mothers of seven NLE children all carrying at least one DQA1 allele with glutamine at position 34 of the first domain compared with just 44% of controls." (PMID 35721085, 2022).
neuropathy (1 paper, 2022). A disorder affecting the nervous system that manifests with pain, tingling, numbness, and/or muscle weakness. "Dead M. leprae increased the expression of WNK, IFNB, IKBKA, and HLA-DQA1 (genes related to neuropathy), in addition to GJA1 and RAF1 (for Schwann cell reprogramming) and KCNJ10, OLIG1, SHH, and SOSTDC1 (for neural regeneration)." (PMID 35492305, 2022).
oropharyngeal cancer (1 paper, 2017). Carcinoma, predominantly squamous cell, arising from the epithelial cells of the oropharynx. "The HLA-DRB1*1301/HLA-DQA1*0103/HLA-DQB1*0603 haplotype has previously been associated with protection from oral and oropharyngeal cancer, particularly in HPV-positive cases (OR = 0.23, P = 1.6 × 10−6)." (PMID 28806749, 2017).
pancolitis (1 paper, 2021). Ulcerative colitis that involves the entire colon. "In UC, the presence of HLA-DQA1*05 was associated with pancolitis at diagnosis (E4, which was 55% more frequent in HLA-DQA1*05-positive patients, p = 0.012)." (PMID 34946883, 2021). "Analysis of HLA-DQA1*05 allele homo- and heterozygosity in the context of polygenic risk scores could help elucidate the interactions between gender and HLA-DQA1*05-related pancolitis in UC." (PMID 34946883, 2021).
parasite infection (1 paper, 2021). "Thus, POR is indirectly responsible for regulation of expression of CIITA along with the molecules of MHC II group such as CD74, HLADQA1, HLADMA, HLADQB1 and HLADRB5 previously identified as genes responsible for inhibition of parasite infection." (PMID 34946170, 2021).
prostate carcinoma (1 paper, 2021). A carcinoma that arises from epithelial cells of the prostate gland. "A total of 20 genes are involved in these intra-category multimorbid relationships and are mainly related to the human leukocyte antigen (HLA) complex (such as HLA-DQA1 and HLA-DRB1), histone clusters (such as HIST1H1B and HIST1H2AJ), and tumors (such as TERT and NOTCH4 for prostate cancer)." (PMID 34225788, 2021).
sarcoma (1 paper, 2024). A usually aggressive malignant neoplasm of the soft tissue or bone. "HLA-DQA1 was reported to be over-expressed in sarcoma, and this over-expression was associated with long-term survival." (PMID 39273632, 2024).
systemic sclerosis (1 paper, 2021). A chronic disorder, possibly autoimmune, marked by excessive production of collagen which results in hardening and thickening of body tissues. "Previous studies indicated that HLA-DQA1 is strongly associated with SLE, systemic sclerosis (SSc) and anticitrullinated protein antibodies (ACPA)-positive RA." (PMID 34367251, 2021).
thymoma (1 paper, 2013). A neoplasm arising from the epithelial cells of the thymus. "Recently, the Class II HLA-DQA1 and DQB1 genes were associated with thymoma-related MG in an Asian population." (PMID 24294607, 2013). "A significant increase of HLA-DQA1*0401 and DQB1*0604 alleles was disclosed in MG patients with thymoma, compared to the ones without thymoma and to the control group." (PMID 24294607, 2013).
triple-negative breast carcinoma (1 paper, 2023). An invasive breast carcinoma which is negative for expression of estrogen receptor (ER), progesterone receptor (PR), and human epidermal growth factor receptor 2 (HER2). "In a study of 47 triple-negative breast cancer (TNBC) patients by RNA sequencing, HLA-DQA1 was associated with improved progression-free survival." (PMID 37434241, 2023).
urothelial carcinoma (1 paper, 2022). A malignant neoplasm derived from the transitional epithelium of the urinary tract (urinary bladder, ureter, urethra, or renal pelvis). "To test the prediction power of those genes, we developed a regression model for urothelial carcinoma that defined a set of 3 genes: NKIRAS2, AKTIP, and HLA-DQA1, which provides the likelihood of development of primary urothelial carcinoma with same estimation for male and female." (PMID 35039759, 2022).
tumor (44 papers, 2009 to 2025). "Variants of HLA-DQA1 may lead to an increase in immune tolerance, which may cause tumor cells to escape from immunosurveillance that exacerbates disease progression." (PMID 38684858, 2024). "However, further research is still needed to validate these findings and elucidate the underlying mechanisms of HLA-DQA1 in tumor development." (PMID 37884883, 2023). "The downregulation of HLA-DQA1, HLA-DOB, and ITM2A, which are associated with immune evasion and tumor progression, is consistent with the immune-excluded phenotype observed in the mesenchymal-like (C5) and aggressive basal/squamous-like (C4) subtypes." (PMID 40867248, 2025). "The higher the expression level of HLA-DQA1 is, the larger the tumour, and the higher the probability of familial disease will be." (PMID 37434241, 2023). "This was further supported by the high levels of MHC I/II molecules (HLA–B, HLA-C, HLA-DRB1 and HLA-DQA1) expressed in cDC-CD1C-AREG from low tumor infiltration group as well as inflammatory cytokines and chemokines (IL1B, VEGF and CCL4, etc.)." (PMID 36532059, 2022). "Since TAP1 and HLA-DQA1 function in antigen presentation processes that allow T cells to recognize and kill tumor cells, we examined the prognostic value of their combined IHC values." (PMID 35173148, 2022). "Increased expression of MHC class II genes CD74, HLA-DMB, and HLA-DQA1 indicate higher tumour antigen processing by the antigen presenting cells in clusters III and IV." (PMID 29050337, 2017). "Expression of TRIM27 and HLA-DQA1 was analyzed with the stratification of different sex, age, family history, high/low-incidence areas, the regional lymph node metastasis and tumor location." (PMID 24595008, 2014). "Meanwhile, HLA-DQA1 is one of the MHC-class-II molecules involved in antigen presentation and immune regulation, and its variant or expression level may affect tumor recognition and attack by CD8Tex cells." (PMID 38684858, 2024). "Our results also demonstrated that radiomics could accurately and noninvasively estimate tumour HLA-DQA1 expression with AUCs of 0.866 and 0.780 in the training and validation groups, respectively." (PMID 37434241, 2023). "Additionally, we conducted in vitro experiments to validate HLA-DQA1 and found it to be a tumor-suppressing gene." (PMID 37884883, 2023). "HLA-DQA1 expression in the tumor tissues of the RCC was significantly higher than that of the LCC." (PMID 35936748, 2022). "Among these subpopulations, the proportions of CFD+ iCAFs, HSPA6+ mCAFs, and HLA-DQA1+ apCAFs were markedly elevated in CRCM, potentially correlating with tumor metastasis." (PMID 40225580, 2025). "The transcriptomic profile that we found in tumour-reactive CD137+ CD8+ T cells suggested an exhausted/activated-like phenotype with increased expression of TNFRSF9, LAG3, PDCD1, TIGIT and HLA-DPA1/HLA-DQA1." (PMID 38986249, 2024). "On the other hand, pRCC showed upregulation of TFPI2, FSTL1, FAS, and PIGR in the epithelial/tumor, C1QTNF3 and GRN in the endothelial, and ITGAX, HLA-DQA1, IL4I1, and CTSC in the immune compartments." (PMID 38703764, 2024). "Cluster Fib_5 prominently expressed MHC-II genes (HLA-DQA1, HLA-DQA2, HLA-DQB1, HLA-DRB5, HLA-DRB1, HLA-DRA, HLA-DPA1, and HLA-DPB1), indicating their role as antigen-presenting cells with tumor-suppressing effects." (PMID 37533434, 2023). "We observed macrophages present in histologically normal colonic epithelium were more likely to be HLA-DQA1+ (a proxy marker for the C1QC+ state), while those present in tumor tissue were more likely to be SPP1+." (PMID 38036590, 2023). "Up-regulated expression of HLA-DQA1 promotes binding to TCR molecules, which is conducive to antigen presentation and the specific killing effect of T cell toxicity in tumor cells." (PMID 35936748, 2022). "We also identified subgroup‐specific differences: TIF‐1γ+ patients showed upregulation of HLA‐G, HLA‐DQA1, and BAGE, the latter being a well‐known tumor antigen present in many cancers." (PMID 34043263, 2021).
tumor (continued). "Meanwhile, HLA-DPA1, HLA-DQA1, HLA-DPB1 and HLA-DMB belong to MHC class II, one of the most important components in tumor-immune interactions." (PMID 33066530, 2020). "Four genes belong to the HLA family: HLA-DQA1, HLA-DRB1, HLA-DQB1, and HLA-F, which were significantly overexpressed in RCC tumor tissues compared with paired adjacent normal tissues." (PMID 25784652, 2015). "Tumor stromal pathways are also in evidence with the common genes including; TLR4, TLR7, HLA-DRA, HLA-DQA1, CXCR4, FOS and TGFB2 (immune surveillance and chemokine pathways) and NF2, ITGA7, PGF, ITGA4, PDGFD and PARVA (focal adhesion)." (PMID 23226201, 2012). "An interferon gene signature was also present in the profiles derived from the tumor epithelium of the ER-positive tumors (e.g., STAT1, IFIT1, IFIH1, IFI27, ISG15, OAS1, OAS3, OASL) and ER-negative tumors (e.g., HLA-DQA1 and HLA-DQB1)." (PMID 19225562, 2009). "The activity of CD8Tex cells directly affects the growth and spread of tumor cells, while the expression of GJA1 and HLA-DQA1 may regulate the strength and direction of immune response." (PMID 38684858, 2024). "We also noticed that MHCII molecule including HLA-DPA1, HLA-DRB1, HLA-DQA1 and CD74 were significantly downregulated in this cluster of macrophages, which may contribute to sub-optimal tumor antigen presentation." (PMID 37957625, 2023). "In concurrence with NanoString analysis of our own tumor samples, these included IFN-γ signaling genes STAT1, CXCL10, and IDO1; antigen presentation molecules HLA-DQA1 and HLA-DRB1; important T cell molecules GZMB and IL7R; and B cell–related molecules CD79A and CXCL13." (PMID 35132960, 2022). "However, analysis of single‐cell RNA‐sequencing (RNA‐seq) of GB patient tumors revealed that tumor cells do not express CIITA nor genes encoding for MHC‐II antigen processing (CD74, HLA‐DMA, HLA‐DOA) and presentation (HLA‐DQA1, HLA‐DQB1, HLA‐DRA, HLA‐DRB1, HLA‐DRB5)." (PMID 39535369, 2025). "Moreover, the antigen-presenting genes HLA-DQA1 and HLA-DQB1 were strongly correlated with pseudotime in IBC tumour-infiltrating myeloid cells, suggesting that IBC tumour-infiltrating myeloid cells may promote humoral immunity by enhancing their antigen-presenting ability." (PMID 40624675, 2025). "In addition, HLA-DQA1 and HLA-F showed prognostic values for overall survival, and HLA-A, HLA-C, HLA-DPA1 and HLA-DQA1 showed prognostic values for recurrence-free survival (all P ≤ 0.05, elevated 0.927, 0.992, 1.023, 0.918, 0.937 multiples compared to non-tumor tissues, respectively)." (PMID 31602270, 2019). "Notably, HLA-II expression in tumor cells was not uniform across the genes examined, with significantly higher HLA-DRB1 than HLA-DQA1, HLA-DQB1, and HLA-DPB1 (p < 0.0001, Kruskal–Wallis)." (PMID 35831288, 2022). "Other proteins, including HLA-A, HLA-DMA, HLA-DQA1, HLA-DQB1, HLA-DRA, HLA-DRB1, and HLA-DRB5, were not reported on tumor–host immunological interactions, which indicated the proteins need further studies to testify them as novel OC biomarkers for tumor immunology." (PMID 31258820, 2019).
cancer (19 papers, 2008 to 2025). A tumor composed of atypical neoplastic, often pleomorphic cells that invade other tissues. "High HLA-DQA1 expression is associated with a better prognosis in many cancers." (PMID 37434241, 2023). "Carriers of the HLA-DQA105 allele exhibited increased immunogenicity when treated with TNFα antagonists, indicating the potential relevance of HLA-DQA1 to immune modulation in cancer therapy." (PMID 41009979, 2025). "Previous studies have proved the expression of HLA-DQA1 decreased in cancer tissue compared with corresponding adjacent tissue and high expression of it was related with better prognosis." (PMID 32793247, 2018). "There are limited data highlighting the role of HLA-DQA1 in carcinoma progression." (PMID 39273632, 2024). "However, the cancer risk associations of HLA-DQA1 are contradictory and not very well understood yet22,58,59." (PMID 39003285, 2024). "As for MHC molecules, we found the MHC class II molecules including HLA-DPA1, HLA-DPB1, HLA-DRA, HLA-DRB1, HLA-DQA1, HLA-DQB1 showed a stronger relation with PD-1 than other MHC molecules in some cancer types." (PMID 30607140, 2018). "Noteworthy were a number of hub genes like TLR4, FAS, HLA-DQB1, HLA-DQA1, F2, HLA-C, IFNAR1, which link complex diseases related to metabolic, immunological, infectious, cardiovascular, neuro-psychiatric disorders and cancer." (PMID 18782426, 2008). "However, high HLA-DQA1 expression is not always a protective factor in cancer." (PMID 37434241, 2023).
infection (8 papers, 2016 to 2025). The state of being infected such as from the introduction of a foreign agent such as serum, vaccine, antigenic substance or organism. "rs1047989 (HLA-DQA1) was significantly associated with a greater number of infections at relapse in SDNS/FRNS patients (P = 0.045, OR = 6.79, 95% CI: 1.29-168.52)." (PMID 40087743, 2025). "rs1047989 (HLA-DQA1) was significantly associated with a greater number of infections at relapse in SDNS/FRNS patients (OR = 6.79, 95% CI: 1.29–168.52, P = 0.045), and the dominant model supported this result (P value = 0.02)." (PMID 40087743, 2025). "Furthermore HLA-DQA1*0102 and *0103 seemed to represent risk factors for infection in Afro-Ecuadorians and HLA-DQA1*0301 was a possible susceptibility allele in the Cayapas population." (PMID 30274490, 2018). "For example, rs1047989 in HLA-DQA1 was significantly associated with a greater number of infections at relapse in SDNS/FRNS patients and with the differential expression of HLA-DQA1 and HLA-DQB1 in the relapse and remission stages of SSNS." (PMID 40087743, 2025). "HLA-DRB, HLA-DQA1, and MICA genes have important roles in the adaptive immune response to infection—coding for MHC class I and II alleles, which are responsible for antigen processing and exogeneous peptide presentation." (PMID 33794208, 2021). "Functional variations in HLA-DQA1 and HLA-DQB1 are implicated in regulating the immune response of SSNS patients, which may explain the typical triggering of SDNS/FRNS onset by infections." (PMID 40087743, 2025). "The HLA-DQA1 heterozygosity may have a protective effect against WNV cases or infection." (PMID 27812212, 2016). "Immune-suppressive phenotypes were also detected in cDCs during infection, with notable downregulation of HLA-DR genes HLA-DRA and HLA-DRB1 along with multiple paralogues (HLA-DPA1/B1 and HLA-DQA1/B1) in cDCs but not cytokine/chemokine genes." (PMID 37968278, 2023).
immune disease (4 papers, 2019 to 2022). "In KEGG, genes associated with immune disease and system include HLA-DQA1, HIST1H2BL, HIST1H2AL, C2, CFB, HSPA1A, TAP2, HIST1H3Jand ATP6V1G2." (PMID 34367251, 2021). "HLA alleles play an important role in auto-immune diseases and the HLA families detected as eGenes from sun-exposed skin tissues were HLA-DQA1, HLA-DRB1, and HLA-DQB1." (PMID 31671645, 2019). "In diseases of the immune system, there were also highly relevant genes, such as HLA-DQA1, HLA-DRB1 and TYK." (PMID 36430729, 2022).
bacterial infection (3 papers, 2016 to 2025). "A strong HLA-DQA1/A2/B1/B2 gene cluster has emerged involving in a broad range of processes including auto-immune disease, viral and bacterial infection, antigen presentation and ER/Golgi/vesicle membrane interaction." (PMID 35386986, 2021). "Nevertheless, there is biological plausibility to the concept of HLA-DQA1 as a marker of bacterial infection." (PMID 27656884, 2016).
skin disorder (1 paper, 2025). Any deviation from the normal structure or function of the skin or subcutaneous tissue that is manifested by a characteristic set of symptoms and signs. "Conversely, the HLA-DQA1*0501:0501 allele was more commonly found in the control group, indicating a potential protective effect in the case of HIV infection with HIV-associated skin disorders." (PMID 40572779, 2025).
HLA-DQA1 also shares sentences with these, for which no sentence is quoted: multiple sclerosis (7 papers); Allergy (4); Obesity (4); type 2 diabetes (4); adenocarcinoma (3); autoimmune thyroid disease (3); Achalasia (2); Iron metabolism disorders (2); lung disease (2); myasthenia gravis (2); Nephropathy (2); neurological disease (2); oral cancer (2); osteoarthritis (2); Parkinson disease (2); soft tissue sarcoma (2); abdominal aortic aneurysm (1); adult onset asthma (1); allergic rhinitis (1); apical periodontitis (1); aplastic anemia (1); atopic dermatitis (1); Basal cell nevus syndrome (1); bladder tumors (1); brain cancer (1); bullous pemphigoid (1); cardiomyopathy (1); chronic hepatitis B (1); chronic myeloid leukemia (1); chronic obstructive pulmonary disease (1).
A further 55 diseases each share a sentence with HLA-DQA1 in 1 paper.